EIF4E (eukaryotic translation initiation factor 4E)
Diseases named in the same sentence as EIF4E in open-access papers (continued):
Sharing a sentence is not in itself a finding about the gene and the disease.
cancer (continued). "Inhibitory activity of MNKs and then the phosphorylation of eIF4E could be an effective and safe target for the treatment of cancers." (PMID 35877722, 2022). "Importantly, altered expression of eIF4E, often upregulated, has been also observed in different kinds of cancers." (PMID 35406615, 2022). "Moreover, increased eukaryotic translation initiation factor (eIF4E) overexpression renders cancer cells resistant to mTOR inhibitors." (PMID 35831271, 2022). "This improves understanding of the role of EIF4E in cancer biology." (PMID 36544768, 2022). "Dysregulation of eIFs and altered expression or activity of components of the eIF4F complex such as eIF4E and eIF4G, have been observed to support cancer cell growth by activating translation initiation of mRNAs encoding key cell cycle regulators, as well as survival and oncogenic factors." (PMID 36348939, 2022). "The overexpression of eIF4E has been found in approximately 30% of human cancer cases." (PMID 36360287, 2022). "Upstream molecular switches, including receptor tyrosine kinases and Ras regulate several positive regulators like PI3K, AKT, mTOR, and eIF4E, which are abnormally activated in many tumorigenesis processes and are involved in controlling the survival, proliferation, and migration of cancer cells." (PMID 35313850, 2022). "Active nuclear export of TSPs and eIF4E-bound oncoprotein mRNAs was effectively blocked by SINE compounds which selectively inhibit XPO1 function, leading to nuclear retention of TSP and eIF4E-bound mRNAs, impeding the cancer growth and prompting selective apoptosis of cancer cells." (PMID 34562230, 2022). "Importantly, in the present study, unlike other ATP-competitive, second-generation mTOR inhibitors, lomitapide was shown to exert anticancer effects on cancer cells with eIF4E overexpression." (PMID 35831271, 2022). "Because eIF4E is the key regulator of translation initiation, it has crucial engagement in the oncogenesis process, and its aberrant expression has also been reported in many cancers." (PMID 36009568, 2022). "eIF4E is a pro-oncogenic protein that is highly upregulated in many cancers." (PMID 34831461, 2021). "In addition, upregulation of PRMT5 activates PI3K, AKT, mTOR/eIF4E, and NF-κB signaling, contributing to the proliferation of cancer cells." (PMID 34006904, 2021). "Proteins located downstream of mTORC1, such as eukaryotic translation initiation factor 4E binding protein 1 (4E-BP1) and eukaryotic translation initiation factor 4E (eIF4E), exert significant control over cap-dependent translation, cell growth, and cancer initiation and progression." (PMID 33482765, 2021). "Importantly, eIF4E phosphorylation has been demonstrated to be important in other cancers, including malignancies of the breast, colon, and prostate." (PMID 34032633, 2021). "Protein synthetic rates are significantly reduced following apoptosis induction, where caspase-dependent proteolytic cleavage and altered phosphorylation states of translation initiation factors (eIF4GI, eIF4GII, eIF4E, eIF4B, and eIF2α) influence cancer progression." (PMID 34526485, 2021). "Notably, dysregulation of the eIF4E/4E-BPs interaction is a common feature of numerous diseases, such as cancer, neuropsychiatric and neurodevelopmental disorders." (PMID 34541613, 2021). "Oncomine, Timer and UALCAN were used to analyze the expression of eIF4E in various cancers." (PMID 34876062, 2021). "Furthermore, several short peptides have been designed, based on the sequence of eIF4E binding partners, to specifically destabilize the eIF4E-eIF4G complex in the cell, representing a valuable approach to target eIF4E-mediated translation in cancer models." (PMID 35582305, 2021). "In transgenic models of eIF4E overexpression, mice develop a variety of cancers; while partial loss of eIF4E does not substantially impact transgenic mice, the complete deletion of eIF4E is lethal." (PMID 34944805, 2021).
cancer (continued). "Increased demand for cap-dependent translation and thus levels of eIF4E might drive cancer cells to change the eIF4E protein stability or eIF4E mRNA translational efficiency." (PMID 33540613, 2021). "The overexpression of eIF4AI and eIF4E has been documented in different cancer types." (PMID 33540613, 2021). "eIF4E levels are increased in many cancers, where it generally correlates with poor prognosis." (PMID 33375634, 2020). "In transgenic models of eIF4E overexpression, mice develop a variety of cancers." (PMID 33375634, 2020). "Focusing on the TCGA pan-cancer study, which includes data from 33 cancer types, we first observed the CNV and mutational profiles of the tumor suppressor RB1, the proto-oncogene MYC, and the translation initiation factor EIF4E." (PMID 33266490, 2020). "In mouse models, eIF4E haploinsufficiency is compatible with normal development but not for transformation, providing a potential explanation for the frequent activation of eIF4E in cancer cells." (PMID 32924027, 2020). "In addition, elevated levels of phosphorylated eIF4E have been found in human cancer tissues obtained from patients with lung, head, colorectal, and gastric cancers and primary pancreatic ductal adenocarcinoma." (PMID 32340135, 2020). "In addition, high-level eIF4E has been identified to relate with the progression of tumor and low survival in several human cancers, such as breast, colon and lung cancers." (PMID 33116125, 2020). "At the transcriptional level, EIF4E is upregulated in 13 cancer types and downregulated in two." (PMID 33266490, 2020). "In this study, we investigated the association between expression of p-Akt, p-mTOR and p-eIF4E proteins and clinicopathological characteristics in 341 cases of NSCLC and 91 cases of non-cancer lung tissues by immunohistochemistry (IHC) using high-throughput tissue microarray." (PMID 32023262, 2020). "Rapamycin is known to increase eIF4E phosphorylation at S209 in many cancer cell types." (PMID 31921404, 2020). "For instance, the eIF4E/LRPPRC-mediated CRM1 pathway is upregulated in many cancers." (PMID 32383752, 2020). "EIF4E is frequently found to be overexpressed in cancer cells and may help increase a translational output that supports tumorigenesis." (PMID 32926483, 2020). "Variability of the responses depending on the heterogeneity of cancers may be involved, which in some way might be related to the initial level of expression of eIF4E protein in cancer cells." (PMID 31825993, 2019). "Some of these RBPs which have been largely studied in cancer development are Sam68, eIF4E, or HuR." (PMID 31027221, 2019). "Interestingly, whereas eIF4E is present in the cytoplasm and in the nucleus in normal cells, the majority of eIF4E is nuclear in cancer cells." (PMID 31795417, 2019). "In addition, Sonenberg and colleagues provided a rationale for targeting eIF4E phosphorylation in both cancer cells and cells that comprise the TME to halt metastasis and demonstrated the efficacy of this strategy using merestinib, and Mnk1/2 inhibitor." (PMID 30832411, 2019). "Both SRC and EIF4E play essential roles in multiple cancers, including NSCLC24,25." (PMID 31375661, 2019). "Direct phosphorylation of eIF4E also plays an important role in cancer development, where mouse studies have demonstrated that mutant eIF4ES209A mice, which are incapable of being phosphorylated by the MNK kinases (1/2), are resistant to polyoma middle-T driven mammary tumours." (PMID 31118010, 2019). "eIF4E expression and/or activity are increased in numerous cancers, playing a prooncogenic role." (PMID 31258849, 2019). "Targeting eIF4E is currently under investigation in many cancer types and might represent a target in GBC therapy." (PMID 31586263, 2019). "Thus, deregulation of AXL/eIF4E in drug-resistant cancer cells invokes ER stress, which in turn activates a stress-relief UPR mediated by the PERK/JNK/ATF2 cascade." (PMID 31431614, 2019).
cancer (continued). "While eIF4E phosphorylation has been shown to be dispensable for normal development and fertility in genetically engineered mouse models, it is critical for cancer development and progression, making it an attractive target for cancer treatment." (PMID 30804329, 2019). "However, surprisingly, it has been suggested that normal levels of eIF4E is responsible for cancer transformation." (PMID 31671902, 2019). "Notably, aberrant expression of a set of mRNAs that are involved in cell proliferation, survival, or promotion of cancer is highly affected by eIF4E-mediated translation." (PMID 31671902, 2019). "Reduction of eIF4E levels by using shRNA reduced soft agar colony formation of human cancer cells." (PMID 31671902, 2019). "It is reported that eIF4E phosphorylation acts a positive role in promoting cancer progression." (PMID 30744688, 2019). "Hence, recently, eIF4E has been considered as the main target for the development of cancer therapy." (PMID 31671902, 2019). "The results further support the notion that in cancer cells with dysregulated eIF4E/4E-BP ratio, administration of asTORi could promote the replication of HSV1-dCIP0." (PMID 30138450, 2018). "PEC shows the down regulation of PI3K/AKT/mTOR pathway which is a major regulator of autophagic and apoptotic cell death in cancer cells that leads to the down-regulation of p-4EBP1, p-p70S6K, and p-eIF4E in PEC treated cells when compared with the untreated cells." (PMID 30096805, 2018). "Thus, pharmacoviral combination of asTORi and HSV1 can target cancer cells displaying dysregulated eIF4E/4E-BPs axis." (PMID 30138450, 2018). "In some cancers, eIF4E is over-expressed to enhance assembly of eIF4F, leading to transformation." (PMID 29301334, 2018). "Activation of eIF4E in tumors regulates not only proliferation, but also evasion from apoptosis, fibrosis and metastasis and targeting of the eIF4F complex is of particular interest in developing new cancer treatment strategies." (PMID 30224299, 2018). "Thus, our data reveal that cancer cells harboring altered mRNA translation via dysregulated eIF4E/4E-BPs axis can be targeted by the combination of asTORi and HSV1-dICP0." (PMID 30138450, 2018). "Docking studies point to 5-NT and EIF4E as possible cancer-related targets." (PMID 30018949, 2018). "Several preclinical studies have reported potential therapeutic tools for the treatment of human cancers, that target the translation machinery, such as mTOR inhibitors (e.g., Rapamycin, Torin 1), eIF4E inhibitors (e.g., 4EGI-1, 4E1RCat), and MNK inhibitors (e.g., Cercosporamide, CGP57380)." (PMID 28961193, 2017). "Thus, targeting elevated eIF-4E function in cancer cells has become an attractive therapeutics strategy for malignancies." (PMID 28054974, 2017). "eIF4E overexpression and translation initiation is involved in malignant transformation and chemo-resistance in vitro and in vivo and thus represents an important target for cancer therapy." (PMID 29100389, 2017). "Indeed, studies have shown that overexpressing eIF4E selectively disables hypoxic tumor cells and eIF4E2 mRNA targets are enriched in cancer-driving genes." (PMID 29317983, 2017). "Nonetheless, due to varying levels of 4E-BPs versus eIF4E in cancer tissues, our results propose an important determinant by which HCC tumors may be inherently resistant, or develop resistance, to metformin through downregulation of 4E-BPs." (PMID 28881582, 2017). "Nonetheless, a number of recent studies, including our own, demonstrate that deregulation of cap-dependent translation by an incomplete inhibition of 4E-BP1 phosphorylation, reduction of 4E-BP1 expression, or upregulation of eIF4E expression renders cancer cell resistance to mTORkis11–16." (PMID 29263324, 2017). "Notably, in several types of cancers such as head and neck and breast cancers, levels of eIF-4E correlate with disease progression and poor prognosis." (PMID 28054974, 2017).
cancer (continued). "Excessive expression of eIF4E is significantly correlated with unfavorable clinical outcomes such as pathological grading of tumor, high cellular proliferation, and poor prognosis in several cancers." (PMID 27588477, 2016). "For these reasons, eIF4E represents an attractive cancer drug target." (PMID 27592390, 2016). "Thus, eIF4E has been proposed to be an oncogene and has been proved to show augment in expression in malignant tumors of many organs such as breast, lung, cervix and colon." (PMID 27907907, 2016). "Small molecule compound 4EGI-1, an inhibitor of the cap-dependent translation initiation through disturbing the interaction between eIF4E and eIF4G which are main elements of the eIF4E complex, has been reported to suppress cell proliferation by inducing apoptosis in many types of cancer." (PMID 26942880, 2016). "Emerging evidence supports targeting 4E-BP1 and eIF4E phosphorylation in cancer." (PMID 26942880, 2016). "In conclusion, combination of targeting both mTOR and Mnk/eIF4E signaling pathways to enhance effectiveness of mTOR-targeted cancer therapy might be significant innovation for the personalized treatment of NSCLC." (PMID 27050281, 2016). "It is implicated that knockdown of eIF4E inhibits cancer cell proliferation in both rapamycin sensitive and insensitive cancer cell without activating AKT24." (PMID 26728896, 2016). "eIF4E proteins was found to mainly locate in cytoplasm of cancer." (PMID 27907907, 2016). "In addition, it has also been reported that the eIF4E/4E-BP ratio is an important factor that determines sensitivity of cancer cells to asTORi17." (PMID 27319316, 2016). "Since mTOR inhibitor induced phosphorylation of eIF4E in a Mnk-dependent manner, combination of mTOR inhibitor and Mnk inhibitor is a promising strategy to improve the efficacy of mTOR inhibitor in human cancers." (PMID 27050281, 2016). "However, only 10% (2/20) of adjacent normal tissues exhibited eIF4E signal, the eIF4E positive cases is only 10% in adjacent tissuses of cancer." (PMID 27907907, 2016). "The combination of targeting eIF4E and traditional anti-cancer agents will be a novel strategy in targeted cancer therapy and may become a promising substitute for the conventional chemotherapy in ESCC." (PMID 27588477, 2016). "Moreover, a recent study suggests that targeting eIF4E for cancer treatment has minimal effects on growth of –and protein synthesis in– healthy cells." (PMID 27592390, 2016). "The ratio of 4E-BP1 to eIF4E is an indicator of rapamycin sensitivity in cancer cells." (PMID 26204490, 2015). "Elevated levels of phosphorylated eIF4E within a tumour are associated with resistance to cell stress and DNA-damaging agents and, as with expression of its binding partner 4E-BP1, with adverse survival outcome in multiple human cancers." (PMID 26501340, 2015). "In addition, these pharmacological probes of p-eIF4E can provide important new insights into the function of p-eIF4E and its mechanism by which p-eIF4E specifically regulates the growth of cancer cells." (PMID 25915158, 2015). "Studies show that both EIF4EBP1 and EIF4E are involved in cancer development and progression." (PMID 25658620, 2015). "Thus, this study concentrated on a particular cancer model and studied the role of eIF4E and eIF4GI in the design of the cells' proteome." (PMID 25717031, 2015). "Considering persistent nature of cancer, we assume that modified binding of H4R3me2s and H3R8me2s at the promoters of eIF4E and FGFR3 may persistently influence oncogene expression in CRC and maintain oncogene-induced tumorigenicity." (PMID 26078354, 2015). "In this way, loss of 4E-BP1 phosphorylation has previously been shown to result in a decrease of Mcl-1 protein expression in various cancer types in vitro and in vivo leading to therapeutic benefit and overexpression of eIF4E led to Mcl-1 expression in our models." (PMID 25627260, 2015).
cancer (continued). "eIF4E and eIF4G specifically, were proven to be critical for translational control, inactivated by stress, activated by growth promoting signals, and often elevated in cancer." (PMID 25717031, 2015). "Overexpression of eIF4E is frequently observed in a variety of human cancers." (PMID 24970798, 2014). "In addition, disruption of cap-dependent translation initiation complex with the selective eIF4E/eIF4G interaction inhibitor 4EGI-1 shows a profound inhibition on Snail expression as well as migratory and invasive abilities of cancer cells." (PMID 24970798, 2014). "We herein report that CDKI-73 targets both CDK9- and eIF4E-related pathways and it may serve as an effective therapeutic agent for the treatment of ovarian cancer, as well as a range of other cancers." (PMID 25277198, 2014). "Accordingly, we are currently investigating whether eIF4E, an oncoprotein often overexpressed in cancer, is directly involved in the control of internal Cx43 translation." (PMID 24884945, 2014). "Our results indicate that this could occur through a reduction in cap(eIF4E)-dependent translation of proteins essential for cancer cell proliferation (e.g. cyclin D1), survival (e.g. survivin) and genome repair (e.g. NBS1)." (PMID 24970821, 2014). "Furthermore, since eIF4E is overexpressed in several types of cancers, it is considered as a primary target for cancer drugs." (PMID 24438646, 2014). "Interestingly, in this study, there was significant higher expression of p-eIF4E in metastatic NPC than that in the matched primary cancer." (PMID 24551240, 2014). "Additionally, surveys of many different human cancer types indicate that eIF4E levels are elevated in malignancies of the prostate, lung, breast, stomach, colon, skin as well as cancers of the hematopoietic system." (PMID 24260583, 2013). "eIF4E activity is regulated by signaling pathways amplified in human cancers." (PMID 22666083, 2012). "Elevated expression levels of eIF4E promote cancer development and progression." (PMID 22392765, 2012). "Pharmacologically, treatment with eIF4E anti-sense RNA or agents that induce phosphorylation of eIF2α inhibits translation initiation and proliferation of cancer cells in vitro, and reduces tumor growth in animal models of human cancers." (PMID 22935625, 2012). "Several studies have shown that treatment of some types of cancer cells with rapamycin (or its analogs) actually increases the phosphorylation of eIF4E which may promote tumourigenesis." (PMID 22392765, 2012). "Levels of eIF4E, eIF4G and eIF4A are frequently up-regulated in human cancers." (PMID 22935625, 2012). "Interestingly, the cap-binding protein eIF4E and its repressor 4E-BP have been involved in numerous cancers including CLL/SLL." (PMID 22235315, 2012). "Thus, targeting PI3K, Akt, Mnk and eIF4E are all reasonable strategies to target these processes.Cancer cells appear to develop an oncogene addiction to eIF4E thereby providing a therapeutic window for targeting this protein." (PMID 24213503, 2012). "Elevated levels of eIF4E have been found in many types of tumours and cancer cell lines including cancers of the colon, breast, bladder, lung, prostate, gastrointestinal tract, head and neck, Hodgkin's lymphomas and neuroblastomas, but not in typical benign lesions." (PMID 22392765, 2012). "While these findings, along with evidence of eIF4E overexpression in human cancers, support the notion that eIF4E is oncogenic, a direct connection between eIF4E and translational deregulation downstream of oncogenic AKT signalling has only recently been described." (PMID 21772331, 2011). "But much of the attention paid of late to eIF4E biology as it pertains to cancer, especially from oncologists and pharmaceutical companies, relates to the anti-neoplastic potential of the macrolide rapamycin (and its analogs) and its cellular target, the master kinase mTOR." (PMID 21378410, 2011).